FMO4 (flavin containing dimethylaniline monoxygenase 4)
Description:
This protein is involved in the oxidative metabolism of a variety of xenobiotics such as drugs and pesticides.
Synonyms: FMO2
Tractability: Antibody: UniProt predicts a signal peptide or a membrane-spanning region. PROTAC: its protein half-life has been measured.
Gene: Protein-coding gene on chromosome 1 (171,314,091 to 171,343,741, forward strand). Ensembl gene ENSG00000076258.
Subcellular location: Microsome membrane; Endoplasmic reticulum membrane
Subcellular location (Human Protein Atlas): Cytosol; Vesicles
Gene Ontology:
Molecular function: monooxygenase activity; protein binding; N,N-dimethylaniline monooxygenase activity; flavin adenine dinucleotide binding; NADP binding
Biological process: xenobiotic metabolic process
Cellular component: endoplasmic reticulum membrane
Genetic constraint (gnomAD): Loss-of-function variants: 30 observed, 30.63 expected, observed/expected ratio (o/e) 0.98, 90% interval 0.73 to 1.33. The upper end of that interval is the gene's LOEUF score, 1.33, which puts it in group 5 of 6, group 1 being the genes least tolerant of losing a copy. Missense variants: 527 observed, 580.84 expected, observed/expected ratio (o/e) 0.91, 90% interval 0.84 to 0.98. Synonymous variants: 202 observed, 208.48 expected, observed/expected ratio (o/e) 0.97, 90% interval 0.86 to 1.09.
Homologues: Orthologues: chimpanzee FMO4 (99% identical), macaque FMO4 (96% identical), dog FMO4 (86% identical), pig FMO4 (82% identical), guinea pig FMO4 (81% identical), rat Fmo4 (80% identical), mouse Fmo4 (80% identical), rabbit FMO4 (78% identical), tropical clawed frog fmo2 (48% identical), Caenorhabditis elegans fmo-5 (37% identical), Caenorhabditis elegans fmo-1 (36% identical), Caenorhabditis elegans fmo-3 (36% identical), and 2 more. Paralogues in human: FMO2 (52% identical), FMO3 (50% identical), FMO1 (49% identical), FMO5 (49% identical), FOXRED2 (20% identical).
Diseases named in the same sentence as FMO4 in open-access papers:
FMO4 is named in the same sentence as 4 diseases in open-access papers, as found by Europe PMC text mining. Sharing a sentence is not in itself a finding about the gene and the disease. The quoted sentences say what the papers report.
osteoporosis (1 paper, 2025). A condition of reduced bone mass, with decreased cortical thickness and a decrease in the number and size of the trabeculae of cancellous bone (but normal chemical composition), resulting in increased fracture incidence. "This study identified key genes linked to osteoporosis, such as FMO4, PSMA4 and VEGFA, and explored their potential molecular mechanisms and regulatory networks." (PMID 40764749, 2025). "In this study, we systematically identified VEGFA, PSMA4 and FMO4 as genes significantly associated with osteoporosis risk using MR, and explored their expression patterns using single‐cell RNA sequencing (scRNA‐seq) data from osteoporosis patients." (PMID 40764749, 2025). "This study identifies FMO4, PSMA4 and VEGFA as key genes associated with osteoporosis, analyses their molecular mechanisms and regulatory networks and elucidates their relationship with the disease." (PMID 40764749, 2025). "Three genes—FMO4, PSMA4 and VEGFA—were significantly associated with osteoporosis risk." (PMID 40764749, 2025). "These immune populations are known to modulate inflammation, bone resorption and remodelling, reinforcing the immunomodulatory relevance of FMO4, PSMA4 and VEGFA in osteoporosis pathophysiology." (PMID 40764749, 2025). "FMO4, a member of the flavin‐containing monooxygenase (FMO) family, has not been widely studied in osteoporosis." (PMID 40764749, 2025).
trimethylaminuria (1 paper, 2024). A rare inborn error of metabolism characterized by the presence of large amounts of trimethylamine in urine, sweat, and breath, resulting in a fishy body odor in affected individuals. "The duplicated regions harbor a total of five protein-coding genes: MROH9 and members of the flavin-containing monooxygenase family, including FMO3 (mutations cause the recessive disorder Trimethylaminuria; MIM 602079), FMO2, FMO1, and FMO4, all located within the chr1_D region." (PMID 39257002, 2024).
tumor (2 papers, 2006 to 2017). "More work is required to elucidate the molecular mechanism by which Fmo4 is over-expressed in CDDO-Im-treated iMycEμ tumor cells and by which Fmo4 might contribute to the catabolism of this compound." (PMID 16759389, 2006).
cancer (1 paper, 2023). A tumor composed of atypical neoplastic, often pleomorphic cells that invade other tissues. "The pan-cancer analysis in TCGA and GEO datasets showed that FMO1 was upregulated, while FMO2 and FMO4 were downregulated in GC." (PMID 37274237, 2023).